RN7SL709P (RNA, 7SL, cytoplasmic 709, pseudogene)
Gene: Miscellaneous RNA gene on chromosome 8 (37,908,738 to 37,909,037, forward strand). Ensembl gene ENSG00000241032.
Homologues: Orthologues: chimpanzee Metazoa_SRP (99% identical), macaque Metazoa_SRP (89% identical). Paralogues in human: RN7SL1 (86% identical), RN7SL2 (85% identical), RN7SL3 (84% identical), RN7SL664P (84% identical), RN7SL122P (83% identical), RN7SL448P (82% identical), RN7SL45P (82% identical), RN7SL597P (82% identical), RN7SL655P (82% identical), RN7SL220P (82% identical), RN7SL493P (82% identical), RN7SL543P (82% identical), and 702 more.